GRB2 (growth factor receptor bound protein 2)
Diseases named in the same sentence as GRB2 in open-access papers (continued):
Sharing a sentence is not in itself a finding about the gene and the disease.
melanoma (13 papers, 2011 to 2025). A malignant, usually aggressive tumor composed of atypical, neoplastic melanocytes. "C-PC antineoplastic effect on melanoma cells is associated with the downregulation of growth factor receptor-bound protein 2 (GRB2)-ERK1/2 pathway." (PMID 35567250, 2022). "In previous researches, several results suggest that Hey1 promotes the invasion and metastasis of melanoma cells by regulating the GRB2/PI3K/AKT pathway." (PMID 39351154, 2024). "In the present study, we investigated the role of Hey1 in influencing human melanoma cells and elucidated that Hey1 promotes migration and invasion of melanoma cells via the GRB2/PI3K/AKT signaling pathway." (PMID 34729100, 2021). "High-throughput RNA-sequencing analysis revealed that inhibition of Hey1 results in decreased GRB2 expression in melanoma cells." (PMID 34729100, 2021). "In summary, our results suggest that Hey1 promotes the invasion and metastasis of melanoma cells by regulating GRB2/PI3K/AKT pathway." (PMID 34729100, 2021). "Intriguingly, in addition to Hey1, we observed GRB2 expression was also significantly increased in the melanoma tissues compared to that of the normal skin tissues." (PMID 34729100, 2021). "One study showed that the cationic KT2 peptide downregulates GRB2 expression to inhibit the migration and invasion of human melanoma cells." (PMID 34729100, 2021). "Here we show that the Notch signaling downstream target Hey1 promotes migration and invasion of melanoma cells via the GRB2/PI3K/AKT pathway." (PMID 34729100, 2021). "Another study indicated that phycocyanin hinders the proliferation of melanoma cells by downregulating GRB2/ERK signaling transduction." (PMID 34729100, 2021). "Among ErbB signaling pathway genes (Supplementary 1), we observed that the mRNA level of the adaptor protein GRB2 was significantly decreased after inhibition of Hey1 in melanoma cells, compared to that of the control." (PMID 34729100, 2021). "In conclusion, our study provides compelling evidence that Hey1 promotes melanoma cell migration and invasion through GRB2/PI3K/AKT signaling cascade." (PMID 34729100, 2021). "We found that c-CBL knockdown resulted in reduced FAK, SRC and GRB2 protein expression in several melanoma cell lines." (PMID 27472394, 2016). "All these networks were associated to intracellular signaling pathways known to be active in MDSCs (SRC, Grb2, Ras, Stat3, NF-κB and MAPKs), some of them melanoma MDSC-specific targets such as STAT3." (PMID 25151659, 2014). "Relatively, few studies have investigated the role of GRB2 in melanoma." (PMID 34729100, 2021). "We found that Hey1 mediates GRB2 to regulate PI3K/AKT signaling in melanoma cells." (PMID 34729100, 2021). "Thus, Gab2 and Grb2 signaling in melanoma cells does enhance oncogenic phenotype; These Gab2-dependent phenotypes are reported to be mediated via the PI3 kinase-Akt signaling pathway." (PMID 21887372, 2011). "However, we propose that Hey1 may augment the expression of GRB2 to promote the invasion and metastasis of melanoma cells." (PMID 34729100, 2021). "In addition, it was confirmed that FAK could bind to Grb2 and regulate the proliferation and invasion of melanoma." (PMID 30479571, 2018). "Last, functional experiments confirmed that Hey1 positively regulates GRB2/PI3K/AKT pathway to influence migration and invasion of melanoma cells." (PMID 34729100, 2021). "Our results showed that bornyl cis-4-hydroxycinnamate inhibited human melanoma cell metastasis through the MAPKs, FAK/PI3K/Akt/mTOR and GRB2 signaling pathways." (PMID 30042328, 2018). "Our data demonstrate that the effects of c-CBL knockdown in melanoma, were accompanied by decreases in the protein and mRNA levels of FAK, SRC and GRB2, suggesting the involvement of the FAK-GRB2-SRC nexus in the consequences of c-CBL alteration." (PMID 27472394, 2016).
melanoma (continued). "Previous studies in melanoma cells have shown that ShcD binds to Grb2 to mediate the Ras-MAPK pathway and Grb2 has also been shown to be important for lineage segregation between the epiblast and the primitive endoderm in the embryo." (PMID 22948967, 2012). "Using system pathway profiling analysis we reveal the molecular network model, which illustrates how different neurotrophin receptor-dependent adaptor proteins, including GRB2, SHC, and GAB1 connect activation of CD271 to the upregulation of AKT3 in CD271+ melanoma-initiating cells." (PMID 31118427, 2019). "Moreover, Grb2 was suggested to bind to FAK and regulate the proliferation and invasion of melanoma." (PMID 30479571, 2018). "Incidentally, Grb2 SH2 domain-binding antagonists were shown in vitro to block HGF-induced migration and invasion in MDCK epithelial cells, metastasis formation of melanoma and prostate cancer cells in vivo, and the motility of human SW620 CRC cells in wound-healing in vitro assays." (PMID 24708867, 2014). "Our results demonstrated that bornyl cis-4-hydroxycinnamate is a potentially useful agent that inhibits melanoma cell migration and invasion, and altered melanoma cell metastasis by reducing MMP-2 and MMP-9 expression through inhibition of the FAK/PI3K/Akt/mTOR, MAPK, and GRB2 signaling pathways." (PMID 30042328, 2018). "In melanoma cells, ERK rebound upon BRAFV600E inhibition may be due to reduction of the ERK phosphatase DUSP6 and receptor tyrosine kinase blocker Spry2, which sequesters the Grb2:SOS complex, preventing the binding of receptor tyrosine kinase." (PMID 26023796, 2015).
prostate carcinoma (13 papers, 2014 to 2025). A carcinoma that arises from epithelial cells of the prostate gland. "GRB2 is considered to be a susceptibility gene for Alzheimer’s disease, and overexpression of GRB2 in prostate cancer suggests poor prognosis." (PMID 36900050, 2023). "Researches have found that GRB2 is associated with shorter survival of patients with aggressive prostate cancer." (PMID 34858477, 2021). "Taken together, these data suggest that overexpression of GRB2 at both the mRNA and protein level is linked to shorter survival of those with aggressive prostate cancer." (PMID 33707553, 2021). "Here, we show that overexpression of GRB2 is linked to shorter survival of patients with aggressive prostate cancer (defined as GS ≧8)." (PMID 33707553, 2021). "Furthermore, in patients with prostate cancer, GRB2 overexpression was linked to shorter recurrence-free survival." (PMID 40768895, 2025). "In Her2-expressing prostate cancer cells, studies in a xenograft model show that inhibition of GRB2, together with the use of anti-tumor agents, suppresses tumor proliferation." (PMID 33707553, 2021). "Another phenolic acid, GA (>50 μM), was reported to have dose-dependent effects in the regulation of intracellular proteins in prostate cancer: these included the inhibition of growth factor receptor-bound protein 2 (GRB2), PKC, NF-κB p65, JNK, ERK1/2, p38 and phospho-Akt." (PMID 38540096, 2024). "It was also hypothesized that overexpression of Grb2 could be used as a novel poor prognostic biomarker in patients with prostate cancer." (PMID 37687413, 2023). "Therefore, we believe that our conclusion, i.e., that overexpression of GRB2 affects clinical outcome of those with progressive prostate cancer, is reliable." (PMID 33707553, 2021). "Next, we examined the TCGA dataset to ascertain whether expression of GRB2 mRNA affects prostate cancer survival." (PMID 33707553, 2021). "Thus, GRB2 is a novel biomarker that predicts shorter survival of patients with aggressive prostate cancer (GS ≧8)." (PMID 33707553, 2021). "However, we found that GRB2 was overexpressed in TCGA prostate cancer samples and obviously correlated with the survival of patients at the later stage of disease." (PMID 34131148, 2021). "Furthermore, SGEF promotes prostate cancer cell progression by interacting with Grb2 for activating ERK pathway and enhancing EGFR stability." (PMID 29454349, 2018). "Therefore, we performed additional IHC analysis on 118 colon and 42 prostate cancer tissues with the anti-pY160 antibody, which shows a clear correlation between disease progression and Grb2 phosphorylation." (PMID 26103942, 2015). "Therefore, we hypothesized that inhibiting GRB2 is a possible therapeutic option for patients with prostate cancer overexpressing GRB2." (PMID 33707553, 2021). "This suggests that GRB2 plays an important role, along with Her2 and other RTK signaling pathways, in the progression of prostate cancer." (PMID 33707553, 2021). "In prostate cancer cells, gallic acid reduced the levels of the following proteins: son of sevenless homolog 1 (SOS1), growth factor receptor bound protein 2 (GRB2), protein kinase C (PKC), NF-κB, c-Jun N-terminal kinase (JNK), ERK1/2, p38-MAPK, and p-Akt (Thr308, Ser 473)." (PMID 30823649, 2019).
cardiac hypertrophy (11 papers, 2011 to 2025). "The Grb2-p38 MAPK pathway is vital to cope with pressure overload-induced cardiac hypertrophy and myocardial fibrosis." (PMID 39863867, 2025). "Over the past decades, there are many studies that explore the alterations of Grb2, especially in renal cell cancer, podocyte fibrosis, cardiac hypertrophy, and myocardial remodeling as we have introduced earlier." (PMID 33829014, 2021). "Such a scenario is supported by recent studies which specifically delineate the pathological mechanism whereby Grb2 promotes cardiac hypertrophy through affecting extracellular-related protein kinase signal pathway." (PMID 33829014, 2021). "Glycogen synthase kinase-3 (GSK-3) is a crucial regulator of cardiac hypertrophy, and 2,5-dimethylcelecoxib (DM-celecoxib) was found to activate Grb2 tyrosine phosphorylated during the aging process stimulated by CD4." (PMID 30669571, 2019). "GRB2 is known to be involved in cardiac hypertrophy and in fibrosis." (PMID 30669571, 2019). "Src can also activate endocytosis through the Shc-Grb2-Sos-Ras pathway by activating the βγ subunit of the G protein downstream of β1-AR, and activate ERK1/2, and leading to cardiac hypertrophy." (PMID 37650260, 2023).
esophageal squamous cell carcinoma (11 papers, 2010 to 2025). Esophageal squamous cell carcinoma (ESCC) is a type of esophageal carcinoma (EC) that can affect any part of the esophagus, but is usually located in the upper or middle third. "GRB2 is a critical upstream linker that promotes Raf phosphorylation that is regulated by NSUN2 in esophageal squamous cell carcinoma." (PMID 36183976, 2023). "However the expression of grb2 was found to be equal in both esophageal squamous cell carcinoma and adenocarcinoma." (PMID 20565814, 2010). "LIN28B also has a similar structure and stabilizes growth factor receptor-bound protein 2 (GRB2) mRNA in an NSUN2-dependent manner in esophageal squamous cell carcinoma (ESCC), thus indicating that it is a potential m5C reader." (PMID 35562754, 2022). "High levels of GRB2 promote the activation of the PI3K/Akt and Ras pathways in esophageal squamous cell carcinoma." (PMID 36183976, 2023). "By stabilizing the mRNA of GRB2, NSUN2 facilitates the development of esophageal squamous cell carcinoma." (PMID 36348434, 2022). "In esophageal squamous cell carcinoma, NSUN2 and LIN28B enhance the stability of GRB2 mRNA in an m5C-dependent manner, thereby facilitating cancer emergence and progression." (PMID 36532062, 2022).
colorectal cancer (10 papers, 2017 to 2025). A primary or metastatic malignant neoplasm that affects the colon or rectum. "Previous study showed that GRB2 can activate PI3K/AKT signaling in colorectal cancer cells 19 and the PI3K/AKT pathway regulates cell differentiation, migration, and invasion." (PMID 34729100, 2021). "GRB2 is upregulated in non-small cell lung cancer and colorectal cancers and regulates tumor progression." (PMID 32692718, 2020). "Grb2 is expressed in colorectal cancer, and is important in its carcinogenesis, while caveolin-1 is positively regulated via the RAS/MEK/ERK pathway in this cancer." (PMID 28933766, 2017). "Grb2 was only identified in colorectal cancer cells (spot 2)." (PMID 32466394, 2020). "This counterintuitive result was well exemplified by the cases of ZEB2 and RAS in the EMT regulatory network, IRS in the signaling network of EGF-EGFR and insulin-IR, MEK and GRB2 in the signaling network of T-LGL leukemia survival, p21 and PDK1 in F2013, and MEK in C2016 colorectal cancer networks." (PMID 31582789, 2019).
leukemia (10 papers, 2009 to 2024). A malignant (clonal) hematologic disorder, involving hematopoietic stem cells and characterized by the presence of primitive or atypical myeloid or lymphoid cells in the bone marrow and the blood. "They found that targeting Grb2 is particularly promising in treatment of leukemia given the large number of activating mutations of tyrosine kinases in leukemia cells." (PMID 32754300, 2020). "Lopez-Berestein and colleagues developed a novel delivery system to effectively administer Grb2 ASO treatment for leukemia." (PMID 39272802, 2024). "From this work, they concluded that PLCγ1 represents a critical downstream pathway for ZNF198-FGFR1-induced disease, and that Grb2 activation was important for BCR-FGFR1 in the induction of CML-like leukemia in mice." (PMID 35574218, 2022). "Previous work demonstrated the dependence of BCR-FGFR1 on Grb2 for CML-like leukemia, and the importance of PLCγ1 for ZNF198-FGFR1-driven EMS like disease." (PMID 35574218, 2022). "The inhibition of Grb2 is a potential target for ASO in leukemia treatment." (PMID 39272802, 2024). "Furthermore, because duplication of the GRB2 gene is common in leukemias, GRB2 is a possible target for therapeutics." (PMID 33707553, 2021). "BP1001 is a dioeoylphosphatidylcholine lipid-encapsulated P-ethoxy-modified ASO that was designed to block the expression of the growth factor receptor-bound protein 2 (GRB2) and, in turn, suppress the activation ERK1 and ERK2 and leukemia progression." (PMID 39528914, 2024). "To elucidate the exact anti-leukemia mechanism of SPOA, we tested the effect of SPOA on the binding of BCR-ABL with GRB2, and the signal activation by BCR-ABL." (PMID 27926512, 2017). "Using IP–MS strategy in NB4 and U937 leukemia cell lines, we identified 49 potential NTAL protein interactors, including a few previously identified, such as Grb2, Lyn, and SHIP1/INPP5D, and new proteins not previously reported as NTAL interactors." (PMID 33971369, 2021).
pancreatic cancer (10 papers, 2015 to 2025). "In summary, our work has demonstrated that miR-329 was downregulated in pancreatic cancer and involved in cell growth by targeting GRB2." (PMID 26885689, 2016). "In the mechanistic study, we identified GRB2 as a direct target of miR-329 in pancreatic cancer cells, and expression of GRB2 was inversely correlated with miR-329 expression in pancreatic cancer patients." (PMID 26885689, 2016). "The GRB2/pERK pathway was mainly involved in the miR-329 mediated anti-proliferation in pancreatic cancer." (PMID 26885689, 2016). "We next investigated the relationship between miR-329 and GRB2 in pancreatic cancer patients by analyzing the expression levels of GRB2 and miR-329 in the tumor tissue collected from 34 patients." (PMID 26885689, 2016). "In general, our study has shed light on miR-329 regulated mechanism and, miR-329/GRB2/pERK is potential to be targeted for pancreatic cancer management." (PMID 26885689, 2016). "Further, we have also observed that the adaptor molecule Grb2 interacts with both HER3 and MUC4 in pancreatic cancer cells, which suggests that HER3/MUC4 association leads to recruitment of Grb2 for HER3/MUC4 mediated downstream signaling pathway." (PMID 26035354, 2015). "Furthermore, simultaneous overexpression of miR-329 and GRB2 in the pancreatic cancer cell and xenograft model demonstrated that the miR-329 mediated anti-proliferation was dramatically diminished by GRB2." (PMID 26885689, 2016). "Interestingly, the phosphorylated level of ERK was declined simultaneously with the reduced expression of GRB2 when miR-329 was overexpressed in pancreatic cancer cells." (PMID 26885689, 2016). "Based on the phenomena that miR-329 limited cell growth and induced apoptosis in our study, we hypothesized that miR-329 attenuated pancreatic cancer proliferation by targeting GRB2." (PMID 26885689, 2016). "WTAP can activate the Fak-Src-GRB2-Erk1/2 and Fak-PI3K-AKT signaling pathways to restrain the chemosensitivity of pancreatic cancer cells to gemcitabine, and Fak inhibitors have been shown to be able to rescue high WTAP-mediated chemo-tolerance to gemcitabine in pancreatic cancer." (PMID 37297015, 2023). "For example, in pancreatic cancer (PC), WTAP can promote chemo-resistance of PC cells to gemcitabine through stabilizing Fak mRNA and activating Fak signaling pathways, including Fak-Src-GRB2-Erk1/2 and Fak-PI3K-AKT pathways." (PMID 33680959, 2021).
non-small cell lung carcinoma (8 papers, 2018 to 2025). A group of at least three distinct histological types of lung cancer, including non-small cell squamous cell carcinoma, adenocarcinoma, and large cell carcinoma. "For example, miR-1258 suppresses tumor progression via the GRB2/Ras/Erk pathway in non-small-cell lung cancer." (PMID 32733928, 2020). "We found that TGF-β1-induced EMT increased GRB2 expression in A549 cells (non-small cell lung cancer)." (PMID 30087284, 2018). "It has also been reported that activated O2−- and H2O2-mediated cell survival in non-small-cell lung cancer (NSCLC) occurs via the c-Met-PI3K-Akt and c-Met-Grb2/SOS-Ras-p38 pathways." (PMID 36358574, 2022).